MPO (myeloperoxidase)
Diseases named in the same sentence as MPO in open-access papers (continued):
Sharing a sentence is not in itself a finding about the gene and the disease.
myocardial ischemia (19 papers, 2009 to 2025). A disorder of cardiac function caused by insufficient blood flow to the muscle tissue of the heart. "In our study of low risk ED patients with suspected myocardial ischemia, the test characteristics for MPO were poor, and MPO performed worse than two markers of myocardial necrosis (i.e., creatine kinase and creatine kinase isoenzyme MB)." (PMID 23675127, 2009). "Myocardial ischemia caused a robust increase in myeloperoxidase (MPO) activity, a specific marker of local neutrophil activity, in comparison with sham-operated rats (56.18±8.01 mU MPO/tissue g, 16.92±4.11 mU MPO/tissue g, respectively; P<0.05)." (PMID 23592614, 2013). "We conducted a prospective, observational study to evaluate whether serum MPO levels predict 30-day adverse cardiac outcomes for low-risk ED patients with suspected myocardial ischemia." (PMID 23675127, 2009). "We hypothesized that the relationship between initial serum MPO levels would correlate with 30-day adverse cardiac outcomes for low risk emergency department (ED) patients with suspected myocardial ischemia." (PMID 23675127, 2009). "In mice with myocardial ischemia and reperfusion, pretreatment of α-tocopherol, i.e., a fat-soluble vitamin with potent antioxidant activity, significantly decreased cardiac ROS production, neutrophil infiltration, and MPO activity." (PMID 38306371, 2024). "The fact that MPO levels were associated with ECV, a surrogate marker of myocardial diffuse fibrosis, suggests the potential role of oxidative stress in the interstitial fibrosis after myocardial ischemia." (PMID 35883722, 2022). "Additionally, MPO limits endothelial-derived nitric oxide bioavailability which impairs coronary vessel dilatation and worsens cardiac ischemia." (PMID 31341419, 2019). "Previous studies suggest that serum myeloperoxidase (MPO) is a potentially useful biomarker to risk stratify troponin-negative patients with suspected myocardial ischemia." (PMID 23675127, 2009). "Our data do not support the use of MPO for risk stratification of a low risk ED patient population with suspected myocardial ischemia." (PMID 23675127, 2009). "We have shown that MPO facilitates neutrophil recruitment by its positive surface charge, which might explain why Mpo−/− mice had lower cardiac neutrophil levels, and obtained consistent findings in models of myocardial ischemia." (PMID 37656254, 2023). "PMN can activate p38 mitogen-activated protein kinase (MAPK) in a HOCl-dependent manner via MPO, which promotes transdifferentiation of fibroblasts to myofibroblasts, key cellular drivers of interstitial collagen production and fibrosis after myocardial ischemia." (PMID 36670895, 2022). "In models of myocardial ischemia–reperfusion, RLN-2 treatment lowers neutrophil infiltration, reduces myeloperoxidase (MPO) activity, decreases lipid peroxidation products such as malondialdehyde (MDA), and helps maintain calcium homeostasis." (PMID 41196672, 2025). "Maximilian Mauler found that serotonin secreted from platelets promote neutrophil degranulation with CD11b externalization and boost myeloperoxidase (MPO) and hydrogen peroxide (H2O2) secretion, which finally aggravated myocardial ischemia/reperfusion injury." (PMID 35410418, 2022). "Moreover, in a rat model of myocardial ischemia and reperfusion injury, sophocarpine was found to limit infarct size post-I/R, accompanied by decreased serum levels of TNF-α, IL-6, IL-10, and myeloperoxidase (MPO) activity, indicating reduced inflammation." (PMID 38746009, 2024). "In summary, our study provides evidence that specific MPO residues are critical for BET and CCl binding and may be exploited for the use of these ligands for therapeutic purposes in myocardial ischemia." (PMID 39204198, 2024).
Anxiety (18 papers, 2015 to 2026). Intense feelings of nervousness, tension, or panic often arise in response to interpersonal stresses. "Specifically, maintaining plasma MPO at approximately 30 ng/mL appears to be optimal, as both higher and lower levels are significantly associated with anxiety." (PMID 40401059, 2025). "Although this study reveals a significant association between plasma MPO and anxiety risk, several limitations should be acknowledged." (PMID 40401059, 2025). "In interaction analyses, the relationship between MPO levels and anxiety risk remained consistent across both males and females, indicating that the anxiety-related effects of MPO are uniform between sexes." (PMID 40401059, 2025). "After comprehensive adjustment for confounding variables, individuals in both the lowest (Q1 ≤ 29.77 ng/mL) and highest (Q5 ≥ 47.3 ng/mL) MPO quintiles exhibited significantly increased anxiety risk." (PMID 40401059, 2025). "Diabetic individuals exhibit heightened susceptibility to MPO-related anxiety, suggesting synergistic neuroinflammatory pathways." (PMID 40401059, 2025). "Given the importance of proinflammatory alterations as underlying mechanisms of anxiety, we decided to investigate the activity of MPO and the levels of pro- and anti-inflammatory cytokines in the PFC and hippocampus." (PMID 36035219, 2022). "Together, these results indicate that MPO KO reduce the risk assessment/anxiety-related behavior in 5XFAD mice." (PMID 31611761, 2019). "Although our study demonstrates a significant U-shaped association between MPO and anxiety risk, it is worth noting that the diagnostic utility of MPO as a standalone biomarker may be limited." (PMID 40401059, 2025). "As a key regulator of immune responses and oxidative stress, the U-shaped relationship between plasma MPO and anxiety risk may be closely linked to its biological functions." (PMID 40401059, 2025). "This suggests that immune imbalance caused by low plasma MPO may contribute to anxiety development, although further research is needed to validate this hypothesis." (PMID 40401059, 2025). "Our objective is to investigate whether plasma MPO is associated with anxiety risk in Chinese adults." (PMID 40401059, 2025). "On the other hand, elevated plasma MPO have been implicated in the progression of various chronic inflammatory diseases, and chronic inflammation is known to significantly increase the risk of anxiety." (PMID 40401059, 2025). "RCS analysis confirmed a nonlinear association (p for nonlinearity < 0.01), with an inflection point at 30 ng/mL: below this threshold, each 1 ng/mL MPO increase reduced anxiety risk (OR = 0.982, CI: 0.970–0.994), while levels above it heightened risk (OR = 1.004, CI: 1.001–1.008)." (PMID 40401059, 2025). "Notably, diabetic patients should be particularly aware of the heightened anxiety risk associated with MPO dysregulation, and anti-inflammatory approaches could be considered as adjunctive interventions to facilitate personalized treatment strategies." (PMID 40401059, 2025). "Furthermore, we identified an MPO concentration of 30 ng/mL as a critical threshold: below this level, MPO appears to exert a protective effect, whereas levels exceeding this threshold are associated with an increased risk of anxiety." (PMID 40401059, 2025). "Furthermore, animal models and cellular experiments could help elucidate the neuroinflammatory and oxidative stress mechanisms underlying MPO-mediated anxiety." (PMID 40401059, 2025). "Since MPO can regulate neuroinflammatory responses, and neuroinflammation is considered a key feature of mental disorders such as anxiety symptoms, exploring the relationship between MPO and anxiety is of significant importance." (PMID 40401059, 2025). "This study investigates the association between myeloperoxidase (MPO) levels and anxiety risk in Chinese adults and explores potential effect modifiers, with implications for neuroinflammatory biomarker-guided anxiety prevention strategies." (PMID 40401059, 2025).
Anxiety (continued). "Evaluating the potential application of antioxidant and anti-inflammatory strategies in MPO-related anxiety management is also warranted." (PMID 40401059, 2025). "Future research should further explore MPO-related neuroinflammatory mechanisms and assess the role of personalized anti-inflammatory therapies in anxiety treatment." (PMID 40401059, 2025). "In MPO-ANCA patients, fatigue was associated with pain as measured by the WPI (p = 0.01), with trends evident for fibromyalgia (p = 0.05) and anxiety (p = 0.05)." (PMID 36890852, 2023). "The FMT form HV also alleviated the IBD/D−-F-induced anxiety-like behavior, IL-6 expression in the hippocampus, corticosterone, LPS, and IL-6 levels in the blood, and colon shortening, myeloperoxidase activity, and IL-6 expression in the colon." (PMID 34650107, 2021). "Our findings reveal that the relationship between plasma MPO and anxiety risk is not linear but instead follows a U-shaped pattern." (PMID 40401059, 2025). "Plasma MPO demonstrates a U-shaped association with anxiety risk independent of cardiometabolic confounders." (PMID 40401059, 2025). "Therefore, this study utilizes large-scale population data to explore the association between plasma MPO levels and anxiety risk, aiming to elucidate the biological significance and clinical relevance of MPO in anxiety." (PMID 40401059, 2025). "First, the cross-sectional design precludes causal inference, and thus we cannot determine whether changes in MPO levels precede or result from anxiety onset." (PMID 40401059, 2025). "Our study confirms that variations in plasma MPO influence anxiety risk; however, rather than a conventional linear relationship, we identified a U-shaped association." (PMID 40401059, 2025). "It is also important to note the possibility of reverse causality, where elevated anxiety symptoms could influence plasma MPO levels, rather than the other way around." (PMID 40401059, 2025). "The low discriminatory performance may stem from the non-linear (U-shaped) relationship between MPO and anxiety, which differs from the typically linear association seen in other inflammatory markers." (PMID 40401059, 2025). "Notably, although our study also found a higher overall prevalence of anxiety among women, sex did not significantly modify the association between MPO levels and anxiety risk." (PMID 40401059, 2025). "Regarding inflammatory mechanisms in anxiety, recent studies have pointed to myeloperoxidase (MPO), an enzyme mainly produced by neutrophils, as an important marker for anxiety since this enzyme is one of the links between oxidative stress and inflammation." (PMID 36035219, 2022). "Although alterations in MPO activity have been observed in anxiety-like behaviors, a systematic investigation into the relationship between MPO and anxiety disorders remains lacking." (PMID 40401059, 2025). "Therefore, sex does not appear to influence the role of MPO in the pathogenesis of anxiety." (PMID 40401059, 2025). "Furthermore, our data showed that gastric iNOS and MPO expression levels were within the same range for depressed and non-depressed patients, as was also observed for HADS anxiety scores." (PMID 36841844, 2023).
peritonitis (18 papers, 2011 to 2025). Inflammation of the peritoneum (tissue that lines the abdominal wall and covers most of the organs in the abdomen). "BSB has been shown to reduce the MPO activity in the peritoneal fluid of rats with induced peritonitis, as well as in an in vitro assay of neutrophil degranulation and lung and gastric tissues, similar to our study findings in colon tissues." (PMID 40943092, 2025). "It was found that the levels of MPO in the PLF were significantly up‐regulated with the progress of peritonitis." (PMID 39225387, 2024). "Acute PMN migration in models of zymosan-induced peritonitis or ligated intestinal loops induced by intraluminal administration of PMN-chemokine CXCL1 was increased over 2-fold in MPO KO compared to wild type (WT) mice." (PMID 33959129, 2021). "That MPO impacts PON1 activity in vivo was previously demonstrated using i.p. injection of zymosan to induce peritonitis." (PMID 34331945, 2021). "To measure RLS-0071’s inhibitory effect on MPO and NETosis in vivo, we evaluated a rat inflammatory peritonitis model mediated by intraperitoneal injection of purified human MPO, P. aeruginosa supernatant, or immune-complexes." (PMID 34242348, 2021). "To better understand the role played by neutrophils in inflammatory diseases, we measured and modulated myeloperoxidase activity and NETs in vivo, utilizing a rat peritonitis model." (PMID 34242348, 2021). "Other monoterpenes such as bisabolol, citral, thymol and hydroxydihydrocarvone also present considerable anti-inflammatory activity, reducing vascular permeability, leukocyte migration, and myeloperoxidase activity during carrageenan-induced peritonitis." (PMID 32423148, 2020). "Anti-inflammatory activity was evaluated by using a carrageenan-induced peritonitis model submitted to a leukocyte migration assay and myeloperoxidase activity (MPO) analysis." (PMID 30915148, 2019). "The peritonitis experimental model was induced by carrageenan following of Myeloperoxidase activity (MPO), Total glutathione and malondialdehyde (MDA), IL-1β and TNF-α levels by spectroscopic UV/VIS analysis." (PMID 29523111, 2018). "The inhibition of TNF-α production along with a decrease in MPO release due to VPA has also recently been found in a peritonitis paradigm in mice." (PMID 24757498, 2014). "The neutrophil migration seen in mice with carrageenan-induced peritonitis was also indirectly determined by MPO activity." (PMID 21799673, 2011). "Moreover, propolis decreased the number of peritoneal neutrophils in carrageenan‐induced peritonitis, an effect confirmed by reduced myeloperoxidase activity." (PMID 34725836, 2022). "We used the peritonitis induced by carrageenan for evaluation of neutrophil migration, and paw edema induced by carrageenan for investigation of other components of the mechanism: MPO activity, nitrite, and cytokines quantifications." (PMID 36432777, 2022). "Besides the inhibition of LT biosynthesis, salvinorin A also inhibited cell infiltration and myeloperoxidase (MPO) and vascular permeability in the peritoneal cavity of the peritonitis mouse model, as well as decreased exudate volume, inflammatory cells, and MPO activity in the pleurisy rat model." (PMID 33546518, 2021). "Furthermore, IRW inhibited serum MPO activity in rats with peritonitis (P <0.05)." (PMID 30719449, 2019). "This is in consistent with a remarkable reduction in leukocytes migration, myeloperoxidase (MPO) activity, TNF-α in the peritoneal fluid of rats with peritonitis and decreasing edema volume induced by carrageenan, dextran, and 5-HT but not histamine." (PMID 35405982, 2022). "To evaluate RLS-0071’s ability to modulate neutrophil release of MPO and inhibit NET formation induced by immune-complexes we adapted the inflammatory peritonitis animal model by injecting preformed immune-complexes IP." (PMID 34242348, 2021).
peritonitis (continued). "Wholemount immunofluorescence staining and confocal analysis revealed that FALCs were the site of extensive recruitment of Ly6G+ Myeloperoxidase+ (MPO) neutrophils, which formed dense cellular aggregates between 6 and 24 h post-induction of peritonitis." (PMID 32294409, 2020). "(−)-α-Bisabolol (100 and 200 mg/kg) significantly inhibited myeloperoxidase (MPO) activity and decreased TNF-α levels in the peritoneal fluid of rats with induced peritonitis." (PMID 29232831, 2017). "Notably, IRW exerted beneficial effects against LPS-induced peritonitis, specifically, by reducing the serum levels of tumour necrosis factor (TNF)-α and interleukin (IL)-6 and myeloperoxidase (MPO) activity (P<0.05)." (PMID 30719449, 2019).
tuberculosis (18 papers, 2008 to 2025). A chronic, recurrent infection caused by the bacterium Mycobacterium tuberculosis. "Therefore, we explored the sensitivity of neutrophil MPO to ameliorate experimental tuberculosis in the susceptible C3HeB/FeJ mouse model in vivo." (PMID 35269694, 2022). "Expanding on the observation made during COVID-19 infection, a positive correlation between MPO and ferritin during tuberculosis after COVID-19 infection suggests a role for ferritin-mediated NET formation." (PMID 40821848, 2025). "Human myeloperoxidase (MPO) was first isolated in 1941 from purulent pleuritis fluid from tuberculosis patients." (PMID 36048150, 2022). "To examine the effect of anti-tuberculosis treatment (ATT) on neutrophil granular proteins (MPO, PRTN3, elastase), we have analyzed their pre and post-treatment systemic levels among TBL individuals." (PMID 34153068, 2021). "Based on the differences observed between human and murine neutrophils, we cannot exclude the fact that MPO inhibition may have a beneficial host-directed therapeutic effect in human tuberculosis." (PMID 35269694, 2022). "Both failure of reducing ROS and subsequently preventing necrosis may provide an explanation for the failure of MPO inhibition to ameliorate the outcome of experimental tuberculosis in vivo in C3Heb/FeJ mice." (PMID 35269694, 2022). "The relevance of MPO-mediated necrotic cell death for tuberculosis pathogenesis may differ between humans and mice and requires future studies and distinct tuberculosis models to reveal whether MPO remains a valid target for host-directed therapy in humans." (PMID 35269694, 2022). "Thus, we employed the murine C3Heb/FeJ model of tuberculosis to study whether MPO inhibition by ABAH can ameliorate tuberculosis pathogenesis in vivo." (PMID 35269694, 2022). "LTF and LCN2 were also induced during a septic shock, and MPO, LCN2, and LTF were used to distinguish between latent and active tuberculosis." (PMID 39409176, 2024). "MPO inhibition alone or as co-treatment with isoniazid, a first-line antibiotic in tuberculosis treatment, did not result in reduced bacterial burden, improved pathology, or altered infiltrating immune cell compositions." (PMID 35269694, 2022). "We found that NETs (DAPI+CitH3+) were abundant in the neutrophilic (MPO+) lung lesions from infected C3HeB/FeJ mice, showing that NET formation correlates with disease severity in other models of increased susceptibility to TB other than in M. tuberculosis-infected mice during GM-CSF blockade." (PMID 33149141, 2020).